RXRA (retinoid X receptor alpha)
Diseases named in the same sentence as RXRA in open-access papers (continued):
Sharing a sentence is not in itself a finding about the gene and the disease.
cancer (121 papers, 1999 to 2025). A tumor composed of atypical neoplastic, often pleomorphic cells that invade other tissues. "Dysregulated methylation of WT1, PLEK2, MRAS, and RXRA in the twin with B‐ALL increases cancer susceptibility." (PMID 38970307, 2024). "A cancer-associated missense mutation in the nuclear receptor RXRα acts by allosteric mechanisms and impacts differently the activity of its dimers, depending on the dimerization partner." (PMID 34820085, 2021). "Serine 260 of RXRα, a consensus phosphorylation site of mitogen-activated protein kinase, is closely linked to RXRα-retarded degradation and the promotion of cancer cell growth in human HCC-derived HuH7 cells." (PMID 30093910, 2018). "Our study highlights the association between SphK2 and abnormal modulation of RXRα/RARβ in cancer cells." (PMID 28465486, 2017). "It has been suggested that the translocation of RXRα from the nucleus to the cytoplasm underlies a unique pathway in the inhibition of growth of various cancer cells." (PMID 28465486, 2017). "We thus suggest that SphK2-induced degradation of RXRα is linked to resistance of cancer cells to ATRA therapy." (PMID 28465486, 2017). "Its activation has been previously associated with good prognosis in different cancers and RXRα synthetic ligands, the rexinoids, have shown promising antitumor activity in preclinical and clinical studies in different cancer types." (PMID 25669983, 2015). "Dysfunctions of RXRα are implicated in the initiation and development of a variety of diseases including cancer." (PMID 26156677, 2015). "The expression level of RXRα is often found reduced in cancer cells and tissues, implying the association of the less RXRα expression and carcinogenesis." (PMID 26156677, 2015). "While results have been mixed concerning associations between variants in the RXR gene and cancer risk, in vitro animal and human studies have shown that elevated levels of RXRA increases the antiproliferative effects of 1,25(OH)2D3." (PMID 19753122, 2009). "To explore the impact of hepatocyte RXRα deficiency on gender-dependent hepatic gene expression, we compared the expression profiles of cancer-related genes in 6 and 24 month old male and female mice." (PMID 18755030, 2008). "Top ten gender-dependent cancer-related genes that have the greatest fold change due to hepatocyte RXRα deficiency." (PMID 18755030, 2008). "To study the impact of hepatoctye RXRα deficiency on cancer-related gene expression in each gender, we have performed microarray analyses using livers derived from 6 and 24 month old male and female wild type and hepatocyte RXRα-deficient mice." (PMID 18755030, 2008). "Collectively, RXRα deficiency could lead to significant changes in expression levels of cancer-associated genes in a gender- and age-dependent manner." (PMID 18755030, 2008). "Furthermore, we showed a complex association between the expression of mRNA for RXRα, RARs, and PPARs in cancer tissue, suggesting interactions and cross-talk between these receptors in tumorigenesis." (PMID 17767717, 2007). "However, the underlying mechanisms by which RXRα and ligands act, especially whether and how they mediate and modulate the causal link between inflammation and cancer remain obscure." (PMID 30931933, 2019). "Moreover, RXRα inhibited glycolytic metabolism in cancer cells, which might be underlying its inhibition of differentiation and carcinogenic features." (PMID 29748541, 2018). "Thus, loss of RXRα expression could further stabilize β-catenin signaling in tumor cells, leading to greater cell proliferation and higher number of invasive cancers associated with 56Fe relative to γ radiation." (PMID 26500891, 2015). "In cancer cells, RARα/RXRα (NR1B1/NR2B1) interacts with Sp1 and Sp3 on the 17β-hydroxysteroid dehydrogenase type 2 (HSD17B2) promoter, and retinoic acid (RA) induces its expression." (PMID 39858066, 2025).
cancer (continued). "RXRα small-molecule modulators have shown great potential as anti-cancer agents and offer new approaches to tumor therapy." (PMID 41003337, 2025). "Studies have shown that the expression of RXRA increases during normal cell differentiation but is typically suppressed in cancer cells." (PMID 40781327, 2025). "Cellular Thermal Shift Assay (CETSA) and molecular docking studies further confirmed that 7i directly bound to RXRα, thereby mediating its anti-cancer efficacy." (PMID 41003337, 2025). "RXRA is increasingly recognized as a promising candidate for the prevention and treatment of various human cancers." (PMID 40781327, 2025). "In this study, we designed and synthesized a series of benzothiazole derivates inspired by the marine-derived natural compound meroterpenthiazole A and evaluated their anti-cancer and RXRα-modulating activities." (PMID 41003337, 2025). "To examine this in our cancer models, we compared the expression of RARα, RARβ, RARγ, RXRα, RXRβ and RXRγ in AB1-HA tumors, which are sensitive to combination tretinoin–CY therapy, and AE17, CT26 and WEHI164 tumors, which are resistant." (PMID 38350880, 2024). "Together, these results suggested that RXRα inhibits cancer cell migration by down-regulating miR-103." (PMID 37735649, 2023). "We also found that there is a novel tumor suppressive RXRα-KRT7-AS-PTEN signaling axis in cancer, and activation of the signaling axis by RXRα agonist berberine inhibits tumorigenesis and enhances apoptosis." (PMID 37185462, 2023). "As a consequence, this dysregulation of RXRα phosphorylation and heterodimerization can contribute to the progression and development of cancers by disrupting normal cell growth control and response to retinoid signaling." (PMID 37645246, 2023). "Following activation by its ligands 15d-PGJ2, PPARγ heterodimerizes with RXRα and exerts antigrowth effects in cancer cells." (PMID 35406808, 2022). "PPARγ/RXRα signal has been proven to inhibit the growth of cancer cells and reduce tumor invasiveness in a variety of cancers." (PMID 36286423, 2022). "A previous study showed that sulindac can also bind to retinoid X receptor-α (RXRα) and induce cancer cell death in an RXRα-dependent manner." (PMID 34410548, 2022). "These sites bind RARA and RXRA in in response to RA-induced differentiation of F9 embryo carcinoma cells." (PMID 34103494, 2021). "A significant difference in the RXRα expression between cancer and para‐carcinoma tissue was observed in all subgroups including gender, age, tumour size and TNM stage except the T0 stage and M1 stage." (PMID 33128348, 2020). "A clinical study showed that RXRα agonist is a potential drug for cancer prevention and malignancies." (PMID 33128348, 2020). "Consistent with its role in cancer development, RXRα is one of the most important targets for the development of pharmacologic intervention and therapeutic applications." (PMID 30931933, 2019). "It has been reported that, the NR4A1 export-related apoptosis is regulated by its heterodimerization with retinoid X receptor alpha (RXRα) in numerous cancer cells." (PMID 31839811, 2019). "This compound can also suppress AKT activation and thereby promote apoptosis of cancer cells in an RXRα-dependent manner by inhibiting tRXRα interaction with the p85α subunit of PI3K in vitro and in animals." (PMID 30093910, 2018). "Recent findings indicate that an N-terminally truncated form of RXRα (tRXRα) produced in cancer cells resides in the cytoplasm, where it promotes the growth of tumor cells." (PMID 30093910, 2018). "Phosphorylation of the RXRA at serine 260 decreases its coactivator recruitment ability, leading to inhibition of RXRA transcriptional activity and enhanced cancer cell proliferation." (PMID 30518934, 2018).
cancer (continued). "Here we demonstrated that RXRα overexpression in cancer cell lines interferes with their metabolism, suppressing enzymes involved in glycolysis which lead to lower rates of glucose utilization and lactate production as well as increased oxygen consumption." (PMID 29748541, 2018). "In connection with the cancer stem cell theory, does this suggest that the cellular mechanism to elevate RXRα be shut down at certain stages during cell differentiation in order for the transformation of stem cells into CSC to occur?" (PMID 29748541, 2018). "In cancer cells, overexpressing RXRα not only inhibited cell proliferation, but also migration and angiogenesis." (PMID 29748541, 2018). "By comparing the impacts of RXRα in cancer cells with those in stem cells on differentiation, angiogenesis, and metabolism, we revealed that RXRα activated multiple cellular events contributing to tumor suppression." (PMID 29748541, 2018). "Compared to the elevated levels of RXRα in adult ECs or differentiated hMSCs, the RXRα levels in cancer cells were found to be much lower, similar to that of hMSCs before differentiation." (PMID 29748541, 2018). "These functions, which are at the crossroad between normal cell development and cancer transformation, make RXRα a possible key cellular component that affects the fate of stem cells between specialization/maturation and carcinogenesis." (PMID 29748541, 2018). "The translocation of RXRα from the nucleus to the cytoplasm represents a unique pathway in the inhibition of cancer growth." (PMID 28465486, 2017). "In HCT-116 cells, nuclear RXRα is exported to the cytoplasm, leading to an apoptotic effect and cancer growth inhibition." (PMID 28465486, 2017). "The translocation of RXRα/Nur77 heterodimer from the nucleus to the cytoplasm leads to cancer apoptosis." (PMID 28465486, 2017). "IGF1 and RXRA are both involved in a pathway named “Pathways in cancer” which is known to be related to CAD." (PMID 27835645, 2016). "RXRα is a promising drug target for cancer therapy, as it has an inner LBP to accommodate “drug-like” small molecule modulators." (PMID 26156677, 2015). "A number of studies have shown that proteolytic cleavage of RXRα is one of the mechanisms for lower expression of RXRα in cancer cells." (PMID 26156677, 2015). "Retinoid X receptor α (RXRα) and its N-terminally truncated version tRXRα play important roles in tumorigenesis, while some RXRα ligands possess potent anti-cancer activities by targeting and modulating the tumorigenic effects of RXRα and tRXRα." (PMID 26156677, 2015). "The truncated RXRα has been described to result from a type II calpain cleavage of the N-terminal domain of RXRα specifically in cancer cells." (PMID 26450852, 2015). "For its physiological activities, we show that N-6 strongly inhibits tumor necrosis factor α (TNFα)-induced AKT activation and stimulates TNFα-mediated apoptosis in cancer cells in an RXRα/tRXRα dependent manner." (PMID 26156677, 2015). "Recently, we reported that RXRα antagonist K-80003 exhibits striking anti-cancer effects by inhibiting the cytoplasmic activation of PI3K/AKT by tRXRα." (PMID 26156677, 2015). "The feasibility of targeting RXRα for cancer therapy has already been demonstrated by Targretin, a synthetic RXR ligand, currently in use for the treatment of cutaneous T-cell lymphoma." (PMID 23875171, 2013). "Similar to PPARγ, RXRα activation profoundly affects multiple cellular activities that are pertinent to cancer including cellular growth, differentiation, apoptosis, and morphogenesis." (PMID 22966225, 2012). "We recently demonstrated that proteolytic cleavage of RXRα resulted in production of a truncated product, tRXRα, which promotes cancer cell survival by activating phosphatidylinositol-3-OH kinase (PI3K)/AKT pathway." (PMID 22545132, 2012).
cancer (continued). "We recently demonstrated that truncated RXRα, tRXRα, resulted from limited proteolytic cleavage of RXRα in several human tumors as well as in a number of cancer cell lines, confers tumor growth advantage due to its activation of PI3K/AKT survival signaling." (PMID 22545132, 2012). "Analysis of downregulated miRNAs in ASCs revealed significant involvement of the canonic pathways, including molecular mechanisms of cancer, axonal guidance signaling, ephrin receptor signaling, and PPARα/RXRα activation." (PMID 22169120, 2011). "Expression of RARα, RARβ, RARγ, RXRα and RXRβ was found in most cell types in gastric mucosa tissues from normal individuals as well as in distal normal tissues from cancer patients." (PMID 10389997, 1999). "Expression of RARα and RARβ were found in three and seven cancer tissues, respectively, and levels of RXRα mRNA were significantly decreased in poorly differentiated cancer tissues." (PMID 10389997, 1999). "Compound 7i displayed the most significant inhibitory activity, while its inhibitory activity dramatically decreased in RXRα-knockout MDA-MB-231 cell lines, suggesting that the anti-cancer activities of 7i against MDA-MB-231 cells acts in an RXRα-dependent manner." (PMID 41003337, 2025). "K-8008, as a sulindac-derived RXRα ligand, could inhibit the 9-cis-retinoic acid (9-cis-RA)-induced transactivation of RXRα and exert potent anti-cancer activity in breast cancer cells and animal models." (PMID 41003337, 2025). "Dysfunctions of RXRα appear in numerous diseases, especially cancer." (PMID 41003337, 2025). "In cancer cells, aberrant phosphorylation events may result in the accumulation of phosphorylated RXRα (p-RXRα), which can escape degradation mechanisms, leading to an excess of non-functional RXR." (PMID 37645246, 2023). "Recently, it has been confirmed that RXRα can directly target and regulate Nrf2 in cancer." (PMID 36555577, 2022). "Overexpression of RXRα in cancer cells inhibited cell proliferation, invasion, and angiogenesis." (PMID 33550205, 2021). "In addition of being silent heterodimerization partners of different NRs, RXRα is a target for cancer prevention and therapy because it interacts with its ligands and regulates signaling of related pathways." (PMID 34832908, 2021). "Our results showed that EPA-PC and EPA-PE promoted the expression of PPARγ and RXRα, indicating that PPARγ might play an important role in the inhibition of cancer cell development by EPA-phospholipid." (PMID 37073266, 2021). "The abnormal activation of the PPARγ/RXRα pathway decreases the activity of immune cell infiltration by inhibiting the expression and secretion of inflammatory factors, thereby hampering immunotherapies using immune checkpoint blockade in patients with cancer." (PMID 33266062, 2020). "Recently, some studies showed irregular expression of RXRα in various cancer tissues." (PMID 33128348, 2020). "In addition, we found that in cancer tissues, the expression of RXRα was significantly different between N0 and N1‐N2 stages." (PMID 33128348, 2020). "FXR and RXRα play important roles in the malignancy of several cancers, including CCA17." (PMID 31964941, 2020). "The RXRα expression was significantly lower in cancer tissues than in para‐carcinoma tissues." (PMID 33128348, 2020). "The truncated form of retinoid X receptor-alpha is found in cancer." (PMID 30931933, 2019). "Interestingly, RXRα is proteolytically cleaved in cancer cells, implying that aberration in RXRα signaling by limited proteolysis plays a role in cancer development." (PMID 30931933, 2019).
cancer (continued). "Consistently, RXRα level was suppressed in cancer cells (~five times lower compared to differentiated hMSC), and its elevation could inhibit the proliferation, migration, and angiogenesis of cancer cells." (PMID 29748541, 2018). "However, the localization of RXRα had been shown to be altered in some cancers by sequestering it to the splicing factor compartments (SFCs), and this caused the loss of its activity." (PMID 29748541, 2018). "Here, using human mesenchymal stem cells (hMSC) as a model for stem cell differentiation, and by comparing with cancer cell lines, we sought to determine the cellular consequences of modulating RXRα during cell differentiation as well as the possible connections with carcinogenesis." (PMID 29748541, 2018). "Different subcellular localization or nucleus-to-cytoplasm shuttle of RXRα may also affect the development of cancer and certain diseases." (PMID 30093910, 2018). "To understand why RXRα was suppressed in cancer cells, we overexpressed it in MCF-7 cells." (PMID 29748541, 2018). "In contrast, the RXRα levels determined in various human cancer cell lines were much lower." (PMID 29748541, 2018). "However, HCT-116Sphk2 cells demonstrate that a different mechanism of RXRα translocation and degradation accounts for cancer cell resistance to ATRA therapy." (PMID 28465486, 2017). "Thus impairment of RXRα either by epigenetic silencing or mutation could impact on the response of transcriptional machinery dictated by specific response elements in genes associated with progression or inhibition of cancer and present important targets for chemoprevention." (PMID 27167203, 2016). "Recently, we showed that calpain II cleaves RXRα to produce a truncated RXRα–tRXRα in cancer cells." (PMID 26156677, 2015). "Moreover, N-6 inhibits tumor necrosis factor α (TNFα)-induced AKT activation and enhances TNFα-mediated cancer cell apoptosis in an RXRα/tRXRα dependent manner." (PMID 26156677, 2015). "Consequently, loss of RXRα is expected to cause disordered cellular proliferation, and indeed, downregulation of RXRα has been widely reported in a number of cancers including CRC." (PMID 26500891, 2015). "However, both promoters are active to some extent in placenta as well several other cancer-derived cell lines and can be both activated by retinoid X receptor alpha (RXRα) in conjunction with liver X receptor alpha (LXR)." (PMID 24304549, 2013). "We recently reported that tRXRα, an N-terminally truncated form of RXRα, could strongly promote cancer cell growth through activation of PI3K/AKT pathway." (PMID 22545132, 2012). "Activation of the PPARγ/RXRα signaling pathway has been shown to inhibit cell growth, decrease tumor invasiveness, and reduce the production of pro-inflammatory cytokines in different cancer types, including colon, lung, pancreatic, prostate, and breast cancers." (PMID 37645246, 2023). "Among the list of co-expressed features of interest, both RARA (retinoic acid receptor alpha) and RXRA (retinoid X receptor alpha) are identified as strong negative correlates, whereas ZNF207, an early developmental factor linked with pluripotency factors, is a strong positive correlate in cancer." (PMID 37894362, 2023). "Indeed, RXRα has been shown to occupy a pivotal role in a wide range of cellular processes, and RXRα ligands have potential as novel therapeutic candidates, especially in cancer." (PMID 36015121, 2022). "Moreover, PPARG, the gene encoding PPARγ, is the only RXRα-heterodimerizing NR gene that exhibited recurrent genomic alterations (amplification) and high expression selectively in muscle-invasive bladder cancer (MIBC) among the cancer types profiled by TCGA." (PMID 28740126, 2017). "Silencing of RXRα could be a sentinel event in some human cancers." (PMID 27167203, 2016).